DPY19L2P2 (DPY19L2 pseudogene 2)
Description:
Probable C-mannosyltransferase that mediates C-mannosylation of tryptophan residues on target proteins.
Synonyms: DKFZp434E092; FLJ36166
Gene: Transcribed unprocessed pseudogene on chromosome 7 (103,175,343 to 103,277,638, reverse strand). Ensembl gene ENSG00000170629.
Subcellular location: Membrane
Diseases named in the same sentence as DPY19L2P2 in open-access papers:
DPY19L2P2 is named in the same sentence as 1 disease in open-access papers, as found by Europe PMC text mining. Sharing a sentence is not in itself a finding about the gene and the disease.
DPY19L2P2 shares sentences with these, for which no sentence is quoted: Sepsis (1 paper).